KRAS (KRas proto-oncogene, GTPase)
Diseases named in the same sentence as KRAS in open-access papers (continued):
Sharing a sentence is not in itself a finding about the gene and the disease.
tumor (continued). "The use of discriminatory multi-target ddPCR assays hereby allows for direct KRAS SNV detection without prior tumor NGS, making it possible to assess tumor dynamics in a time-relevant co-clinical setting analogous to CA 19-9 levels." (PMID 39795577, 2024). "KRAS mutation has been associated with a poor prognosis in CRC, and so has BRAF mutation, irrespective of MSI status, with BRAF-mutated MSS tumours showing the worst prognosis." (PMID 38040818, 2024). "The tumor microenvironment (TME) in NSCLC, featuring regulatory T cells and myeloid-derived suppressor cells, can create an immunosuppressive landscape that enhances PD-L1 expression, complicating responses to both KRAS G12C inhibitors and PD-L1 therapies." (PMID 39518114, 2024). "As there was no targeted therapy for KRAS mutant tumors before, the clinical activity of sotorasib and adagrasib is considered as a breakthrough in these tumor types." (PMID 38278976, 2024). "The safety and tolerability of KRAS-G12D-specific TCR-T cells were tested in a patient with pancreatic cancer with tumor regression, no toxicity described after 6 months, and persisting TCR-engineered T cells in the circulation." (PMID 39769267, 2024). "To elucidate the differences in KRAS, ATR, CHEK1 mRNA expression levels between the two analyzed group of samples, we checked for their correlation with tumor grade differentiation and depth of myometrium invasion, which are key clinicopathological indicators of tumor progression." (PMID 38669256, 2024). "Additionally, regulating the microbiome within the TME is becoming increasingly valued in tumor therapy, making ETBF and potential biomarkers as therapeutic targets in KRAS-mutant CRC." (PMID 39523457, 2024). "Targeted therapies can reverse immune evasion programs in KRAS-mutant tumours, clearly operating through cell-autonomous and non-cell-autonomous mechanisms, which can be enhanced by combination with ICB." (PMID 36864508, 2023). "Interestingly, the overall tumor suppressive landscapes of BRAF- and EGFR-driven lung tumors were dramatically different from each other as well as from oncogenic KRAS-driven tumors." (PMID 37828026, 2023). "According to the results of the GSVA, M/PDA cells were mainly enriched in cancer-related signalling pathways contributing to tumour growth, proliferation, and metastasis, such as the epithelial-mesenchymal transition, E2F targets, PI3K/AKT/mTOR and KRAS signalling pathways." (PMID 37225691, 2023). "However, re-expression of miR-193a-3/5p reduced the viability of various melanoma cell lines by targeting KRAS, MTOR, and MCL1, thus highlighting the tumor-suppressive role of this miRNA." (PMID 37409119, 2023). "Other clinicopathological features, including age, tumor site, KRAS status, dosage of fruquintinib, and treatment line, did not affect the clinical efficacy of TAS-102 combined with fruquintinib." (PMID 38202064, 2023). "All these suggest that in the oncogenic KRAS-driven mouse PC model iASPP, as an inhibitor of p65RelA, is unlikely to modulate tumour initiation and progression solely via p65RelA." (PMID 37270580, 2023). "Inhibition of downstream signalling and proliferation was restricted to cancer cells harbouring mutant KRAS, and drug treatment suppressed KRAS mutant tumour growth in mice, without having a detrimental effect on animal weight." (PMID 37258666, 2023). "Results showed that in addition to hyperactive RAS signaling, KRAS mutant samples versus KRAS wild‐type counterparts had a significant decrease in CD8+ T‐cell density within tumor tissue, but no discernible difference within the invasive margin." (PMID 36599679, 2023).
tumor (continued). "In addition, as a KRAS signal inhibitor, AMG-510 was shown to promote anti-tumor immunity by inhibiting the PD-L1 signal." (PMID 36982415, 2023). "In the current study, we found that KRAS mutation, OS, DFS, and TME, but not tumor site, were related to DMMR status." (PMID 36937571, 2023). "A small number of control tumours (in which CIN was not experimentally induced) were also able to persist following KRAS inhibition." (PMID 37721639, 2023). "For this reason, mutant selective KRAS inhibitors, which target KRAS only in the tumor cells and not the immune system, are expected to be more promising candidates for combination with immunotherapy than pan RAS, MEK, or ERK inhibitors." (PMID 37581538, 2023). "One other important limitation is that the location of the primary tumor or biomarkers other than KRAS were not considered in this meta-analysis." (PMID 37644249, 2023). "Despite its high ssGSEA KRAS activity scores, EMT tumor 1356 possessed no KRAS mutations or mutations in genes elsewhere in the RAS pathway." (PMID 37805590, 2023). "In KRAS-mutant PDAC, inflammatory mediators (e.g., cytokines, DAMPs, and immune cells) are involved in pro- or anti-tumor gene modulation to sustain a favorable inflammatory TME for tumor growth and development." (PMID 37893166, 2023). "While the tumor suppressive effects of inactivating Pten, Rnf43, and Apc are consistent with previous data on these genes and/or related pathways in BRAF-driven lung cancer, the general decreases in magnitude relative to oncogenic KRAS were unexpected." (PMID 37828026, 2023). "In our study, only 22 patients benefited from NGS analyses; no tumor exhibited microsatellite instability (MSI), and the most frequent mutation (n=5 patients) was in the KRAS gene (G12V and G13D)." (PMID 36741023, 2023). "In the present study, we identified that HIF1A-As2 and MYC form a double-regulatory loop that enhances cell survival, tumor growth and metastasis, suggesting targeting HIF1A-As2 could be a vulnerability in KRAS-dependent NSCLC." (PMID 37041291, 2023). "Nine variants reported in the tumor tissue across EGFR, KRAS, BRAF, and PIK3CA were not covered by the UltraSEEK® Lung Panel." (PMID 37686200, 2023). "However, in our recent in vivo study, we demonstrated a gender-specific correlation between STAT3 expression and KRAS-mutant NSCLC; female mice with tumor-cell-specific STAT3 deletion showed decreased tumorigenesis while males had the opposite outcome." (PMID 36899885, 2023). "CAIXhigh phenotype was associated with mutant KRAS status and lack of pathological regression (WHO Tumor Regression Grade 4 and 5)." (PMID 36768903, 2023). "Through the suppression of miRNAs targeting various TME signaling, tumor cells together with CAFs and TAMs orchestrated KRAS induced tumor promotion, ECM remodeling, epithelial-mesenchymal transition as well as immunosuppression in PDAC TME, which favors tumor promotion." (PMID 37007745, 2023). "Melatonin is found to regulate the immunosuppressive tumor microenvironment (TME) by inhibiting the YAP/PD-L1 axis, and it may be a novel therapy for KRAS-mutant NSCLC." (PMID 36675641, 2023). "Different from KRAS and BRAF (V600E) mutation, none of the clinical characteristics, such as age, gender, tumor sites, histological type, differentiation, TNM stage, lymphovascular invasion, and perineural invasion, was associated with NRAS mutation." (PMID 36862900, 2023). "Using different mouse tumor models, including allograft mouse models, GEMMs, and PDX mouse models, we provide a therapeutic strategy by combining MEK and autophagy inhibition for the treatment of LKB1-mutant KRAS-driven NSCLC." (PMID 36702816, 2023).
tumor (continued). "DFS was worse in patients with high TSR and KRAS wt tumours, compared to TSR-low/KRAS wt." (PMID 37344790, 2023). "KRAS, which can be regarded as a rheostat in cells due to its dependence on the number of active molecules, can be utilized as a biomarker to predict the prognosis of PAAD or as a target for tumor therapy." (PMID 38077303, 2023). "DESI-MSI exposed a specific decrease in glutamine in APC KRAS tumour epithelium, which was not revealed by untargeted LC–MS." (PMID 37580540, 2023). "As a result, HER3 inhibition led to significant anti-cancer effects in both KRAS wild-type and KRAS-mutant mCRC cells, and seribantumab, a humanized HER3 antibody, decreased tumor growth and sensitized tumors to fluorouracil chemotherapies in a liver injection orthotopic mCRC model." (PMID 37163206, 2023). "mRNA levels of RASs (KRAS, HRAS, and NRAS) in LUAD patients with different tumor stages." (PMID 38206735, 2023). "Whereas KRAS oncogenes appear to be responsible for the initiation of lung and pancreatic adenocarcinomas, in colorectal tumors, they are involved in tumor progression, not initiation." (PMID 36928090, 2023). "We found that KRAS sequence variation was associated with negative prognostic outcomes in CRC, with greater increases in hazards for YO and distal tumor location." (PMID 38032636, 2023). "Other clinicopathological characteristics, such as sex, tumor location, histological type, budding grade, MSI, KRAS mutation, and BRAF mutation, were not significantly different." (PMID 36900176, 2023). "However, after KRAS inhibition, CIN-induced tumours were significantly more likely to relapse after treatment than those without CIN induction." (PMID 37721639, 2023). "Importantly, treatment with ASO improved the in vivo persistence of transferred cells in KRAS mutant tumors, and thus a combination of ASO and adoptive transfer with tumor‐reactive T‐cells significantly inhibited tumor growth." (PMID 36599679, 2023). "Taken together, these data suggested that KRAS signaling can suppress miR-34a expression via the PI3K/STAT3 axis, which in turn relieves miR-34a–dependent repression of CD47, leading to escape from innate immune surveillance and tumor progression." (PMID 36413402, 2023). "The combination therapy of neratinib (an EGFR/ERBB2 inhibitor) and cobiotinib (a MEK inhibitor) exhibited synergistic anti-tumor proliferation exclusively in organoids derived from patients with high KDS30 mt KRAS rather than low ones." (PMID 37941550, 2023). "Compared to untreated cells or tumor cells treated with rabbit IgG negative control, tumor cells treated with anti-KRAS antibody showed weaker SOX9 cytoplasmic staining and less nuclear localization." (PMID 37051535, 2023). "Likewise, in Brown tumours, the interplay between reactive and neoplastic cells may play a role in sustaining growth, and it might be speculated that OFC is the non-neoplastic precursor lesion that can turn into a Brown Tumour following the induction of the KRAS mutation." (PMID 37627135, 2023). "Meanwhile, KRAS wild-type tumor cells do not show obvious alterations in KRAS localization (data not shown)." (PMID 37051535, 2023).
tumor (continued). "Through gain and loss of function approaches, we identified that lncRNA HIF1A-As2, a KRAS-induced lncRNA, is required for cell proliferation, epithelial-mesenchymal transition (EMT) and tumor propagation in non-small cell lung cancer (NSCLC) in vitro and in vivo." (PMID 37041291, 2023). "KRAS‐WT and KRAS‐MT tumor tissues displayed no obvious differences in METTL14 mRNA levels (Fig EV1F)." (PMID 36794620, 2023). "Thus, mutant KRAS communicates with macrophages via the CD47/SIRPα axis and renders tumor cells insensitive to phagocytosis by macrophages." (PMID 36413402, 2023). "This study also performed in vivo testing of MCI-062 on a syngeneic mouse model of KRAS-driven CRC (CT-26) and demonstrated that MCI-062 acted on its target, reduced GTP-RAS, suppressed the activation of the MAPK signaling pathway, and inhibited tumor growth." (PMID 37569406, 2023). "In KRAS-mutant LUAD with LKB1, CPS1, an enzyme responsible for carbamoyl phosphate synthesis in the mitochondria, is highly expressed, and the heightened Gln metabolism contributes to rapid tumor growth through increased nucleic acid synthesis." (PMID 37675220, 2023). "It has been reported that oncogenic activation of KRAS/BRAF/MEK signaling stimulates Wnt/β-catenin pathway by β-catenin/TCF4 complex activation via Frizzled co-receptor LRP6 phosphorylation, which in turn promotes tumor growth and invasion." (PMID 37483610, 2023). "In KRAS mutant NSCLC, FAO is facilitated by the upregulation of long-chain acyl-CoA synthetase 3 (ACSL3), the enzyme responsible for activating free FAs, allowing tumor cells to meet the increased ATP demand." (PMID 36675307, 2023). "Based on our RNA-sequencing data, the Hallmark GSEA results indicated that BLACAT3 knockdown enriched EMT, IL6/JAK/STAT3, inflammatory response, KRAS, and TNFA/NF-κB pro-inflammatory signaling along with other gene sets related to tumor angiogenesis and metastasis." (PMID 37612524, 2023). "Moreover, KRAS mutant CRC exhibited an inverse correlation between lactic acid concentrations and tumor‐infiltrating cytotoxic CD8+ T‐cells." (PMID 36599679, 2023). "While the specific role of CRAF dimerization-dependent activation in KRAS mutant tumors is evident, it remains intriguing that not every RAS-mutated tumor relies on CRAF activation." (PMID 38111008, 2023). "Although they both inhibit cell growth and downstream signaling of the MAPK pathway in KRAS-G12C mutant tumor cell lines, ARS-853 is not suitable for use in animal models because of its lack of chemical and metabolic stability." (PMID 37662925, 2023). "The expression of mutant KRAS gene in stromal, non-glandular and basal-like subtypes was high, and was closely related to an extremely aggressive tumor type and undifferentiated phenotypes of PDAC histology." (PMID 37304241, 2023). "In patient 2, KRAS c.38G>A p.G13D was covered by the assay but not detected in the t = 0 tumour biopsy, while in the resection specimen, it was detected with a VAF of 31.8%." (PMID 36196486, 2023). "Last, the inhibitor attenuated tumour growth in mice bearing KRAS G12C, G12D, G12V and A146V mutant models, without causing apparent toxicity to the mice (at least as determined by monitoring animal weight)." (PMID 37258666, 2023). "In addition, more importance was placed on all molecular markers (MSI, KRAS and BRAF) and tumour markers (CEA, CA19.9, CA125) but to a lesser magnitude (i.e. < 10% difference from general cohort responses)." (PMID 37020095, 2023).
tumor (continued). "In most studies, patients with mutations in KRAS, but not NRAS, have had a higher bone marrow (BM) tumor burden and shorter survival." (PMID 37212518, 2023). "We confirmed the tumor suppression effect of TUS-007 in subcutaneous xenograft models of hu-man colon cells (KRAS G12V) with intraperitoneal administrations and in orthotopic xenograft models of human pancreatic cells (KRAS G12D) with oral administrations." (PMID 37513471, 2023). "In addition to these molecules, previous studies confirmed that the Kirsten rat sarcoma viral oncogene homolog (KRAS), transforming growth factor beta (TGF-β), and STAT3 pathways also played a key role in tumor glucose metabolism." (PMID 36124026, 2022). "Relative expression of KRAS was almost identical in both tumor tissues and adjacent mucosa (data not shown)." (PMID 35628513, 2022). "In the third PDAC used in proteomic analysis, C3L-01158, percent of KRAS VAF of 2.7% in bulk, 4.4% in cored, and 17.3% in LMD tumor tissues were observed, respectively, representing 5.4%, 8.8%, and 34.6% neoplastic cellularity in the bulk, cored, and LMD tumors." (PMID 36266629, 2022). "We first used Connectivity Map (CMap) dataset to identify compounds for which the gene expression patterns were opposite the KRAS subtype-specific expression patterns (i.e., gene expression was increased in KM1 or KM2 subtype tumor tissues but decreased after treatment with the compound)." (PMID 35836817, 2022). "Our data revealed that, in contrast to what has previously been described regarding the capacity of mutKRAS cancer cells to modulate the tumor immune microenvironment, the pro-tumorigenic features of fibroblasts are mainly regulated by CRC cells independently of oncogenic KRAS." (PMID 36010567, 2022). "We sought to understand general practice patterns, the influence of molecular diagnostics (e.g., testing for KRAS, NRAS, BRAF, and MSI), tumor sidedness, and patient-centric factors on treatment selection utilizing in-person surveys and three hypothetical patient case scenarios." (PMID 36005180, 2022). "KRAS mutations cause continuous activation of the EGFR intracellular pathway and promote tumor growth and survival, regardless of pharmacological blockade of the EGFR receptor." (PMID 35312176, 2022). "Therefore, further studies to evaluate the anti-tumor effect of combination therapy with OBP-702 and PD-1 blockade using KRAS-mutant murine PDAC tumors with massive stroma are warranted." (PMID 36212775, 2022). "Genetic alternations in KRAS could aberrantly activate the RAS-MAPK signaling axis, which may facilitate tumor initiation and promote early relapse after neoadjuvant chemotherapy." (PMID 36439454, 2022). "The gold dashed line represents the patients with KRAS and BRAF wild-type (double wt) tumours." (PMID 34887523, 2022). "Upstream RTK regulators (EGFR, HER2, FGFR, cMET, and SHP2), direct mediators of KRAS activation (AURKA), and/or effectors of MAPK and PI3K pathways may escape form KRAS G12C inhibition, with different mechanisms depending on the tumor tissue type." (PMID 35267628, 2022). "The KRAS levels in tumor tissues excised from the DXI-treated group were significantly lower than those in the untreated group, showing the correlation of its anti-tumor efficacy with the decrease in KRAS levels." (PMID 35546148, 2022). "However, ERK1/ERK2 inhibition in association with CQ enhanced the autophagy-inhibitory activity of the latter in vitro, blocking tumor progression and extending survival using HCQ in KRAS-mutant pancreatic subject-PDX." (PMID 35159234, 2022).